BAG3 (BAG cochaperone 3)
Diseases named in the same sentence as BAG3 in open-access papers (continued):
Sharing a sentence is not in itself a finding about the gene and the disease.
pancreatic cancer (continued). "We propose BAG3‐H2L4 antibody as a potential clinical candidate for BAG3‐targeted therapy in pancreatic cancer." (PMID 30973679, 2019). "We and others have reported that BAG3 expression is an independent poor prognostic factor with respect to overall survival in patients with pancreatic cancer." (PMID 31001483, 2019). "We have previously shown that secreted BAG3 is a potential target for the treatment of pancreatic ductal adenocarcinoma and that pancreatic tumor growth and metastatic dissemination can be reduced by treatment with an anti‐BAG3 murine antibody." (PMID 30973679, 2019). "Further, we found that key nodes of regulation by our confirmed hits in this interaction map were known molecules that modulate survival, EMT and drug resistance in Ras mutated pancreatic cancers, such as YAP1, SIRT1, BAG3, ILK, CDK5, HDACs or GSK3β." (PMID 30325918, 2018). "BAG3 is aberrantly expressed in several solid tumors and germ cell leukemias, and has been proposed as a potential therapeutic target in cancers including glioma, pancreatic cancer, and ovarian carcinoma." (PMID 40873580, 2025). "In PDAC, pancreatic cancer cell-secreted BAG3 activates macrophages via IFITM2-mediated signaling pathways such as PI3K and p38 MAPK phosphorilation, increasing tumor development and metastasis in a way that can be inhibited by a specific anti- BAG3, neutralizing monoclonal antibody." (PMID 40507324, 2025). "The overexpression of the co-chaperone BAG3 (BCL2 Associated Athanogene 3) has also been described as associated with pancreatic cancer aggressiveness, and its sera levels are measurable in pancreatic cancer patients." (PMID 37835519, 2023). "Notably, in heterotopic allografts of murine pancreatic cancer cells in immunocompetent syngeneic mice, treatment with the anti-BAG3 mAb sensitizes the tumors to the effect of an anti-PD-1 antibody." (PMID 35241649, 2022). "Interestingly, Li and colleagues reported that BAG3 signal was positively correlated with αSMA staining as demonstrated by immunohistochemistry on tissues specimens of pancreatic cancer patients." (PMID 34741483, 2022). "Given that BAG3 might regulate IL-8 expression in PDACs, western blot were performed to evaluate the relationship between BAG3 and IL-8 in fresh pancreatic cancer specimen." (PMID 30154469, 2018). "In pancreatic cancer tissues, BAG3 expression was positively correlated with IL-8 expression." (PMID 30154469, 2018). "A nuclear localization of a small BAG3 subpool could be observed in some cell types, such as glial cells or pancreatic carcinoma cells." (PMID 28680391, 2017). "Importantly, BAG3 expression positively correlated with fibrosis in pancreatic cancer tissue." (PMID 31001483, 2019). "Consistently, delivering the humanized anti-BAG3 antibody BAG3-H2L4 abrogates this binding and leads to a prominent growth reduction in the Mia PaCa-2 pancreatic cancer cell xenograft model." (PMID 37444617, 2023). "The expression levels of BAK1, ITGA3, BAG3, and APOL1 were statistically increased in pancreatic cancer samples versus normal samples, while those of RAB24 was decreased." (PMID 35488119, 2022). "In conclusion, our findings show that the blockades of BAG3/BAG3R and SIRPα/CD47 axes converge in eliciting a sound anti-tumor immune response against pancreatic cancer and in countering tumor growth and the metastatic process." (PMID 35241649, 2022). "BAK1, ITGA3, BAG3 and APOL1 were highly expressed in most pancreatic cancer and pancreatic ductal adenocarcinoma cell lines, while RAB24 was poorly expressed." (PMID 35488119, 2022). "Showing the promising results of these approaches, anti-BAG3 and anti-PD1 treatment with targeted antibodies in a mouse model reduced pancreatic tumor volume along with an increase in CD8+ T cells." (PMID 34831344, 2021). "Our results reveal a novel pathway linking BAG3 expression to enhanced PDAC metastasis, thus making BAG3 a potential target for intervention in pancreatic cancer." (PMID 30154469, 2018).
pancreatic cancer (continued). "Compared with those from the normal controls, immunohistochemical results from the pancreatic tissues revealed statistical increases in the expression of BAK1, ITGA3, BAG3, and APOL1 in pancreatic cancer patients; no immunohistochemical data were available for RAB24." (PMID 35488119, 2022).
pancreatic ductal adenocarcinoma (15 papers, 2015 to 2025). An infiltrating adenocarcinoma that arises from the epithelial cells of the pancreas. "Depletion of Bcl-2 associated athanogene 3 (BAG3) impairs ISG15 translation in pancreatic ductal adenocarcinoma (PDAC) cells, suggesting the role of BAG3 in the control of ISG15 expression." (PMID 36319753, 2022). "Aberrant expression of Bcl-2-associated athanogene 3 (BAG3) can reprogram glucose metabolism in pancreatic ductal adenocarcinoma, thus increasing expression of Hexokinase II (HK-II) which is the first key enzyme of glycolysis by inducing IMP3 recruitment." (PMID 35090515, 2022). "Bcl-2 associated athanogene 3 (BAG3) is highly expressed in pancreatic ductal adenocarcinoma (PDAC), and its high expression appears to be a poor prognostic factor for patients with PDAC." (PMID 30154469, 2018). "Specific tumor types such as endometrial, pancreatic ductal adenocarcinoma, and prostate cancers show near-universal BAG3 expression." (PMID 41367874, 2025). "Previous research demonstrated that BAG3 maintains the active state of pancreatic stellate cells (PSCs) and aids pancreatic ductal adenocarcinoma (PDAC) spread via cytokine release." (PMID 39198407, 2024). "A secreted form of BAG3 has been identified in studies on pancreatic ductal adenocarcinoma (PDAC), the form of cancer most often associated with BAG3." (PMID 36980278, 2023). "We also reported that BAG3 is released by pancreatic ductal adenocarcinoma (PDAC) cells and is detectable in serum samples from PDAC patients." (PMID 30973679, 2019). "Recently, it has been reported that pancreatic ductal adenocarcinoma cells are able to release BAG3 which activates macrophages via its binding to the receptor IFITM-2 (interferon-induced transmembrane protein 2)." (PMID 28680391, 2017). "BAG3 is correlated with poor prognostics in patients with pancreatic ductal adenocarcinoma (PDAC), however, the exact mechanisms remain largely unknown." (PMID 31001483, 2019). "Pancreatic ductal adenocarcinoma (PDAC) has been shown to produce large quantities of BAG3s and the levels of BAG3 are inversely related to survival." (PMID 36980278, 2023). "By analyzing biopsies of pancreatic ductal adenocarcinoma (PDAC) patients, enhanced intracellular BAG3 expression was found to correlate with poorer survival." (PMID 28680391, 2017).
ovarian carcinoma (14 papers, 2018 to 2025). A malignant neoplasm originating from the surface ovarian epithelium. "In another study, cisplatin resistance was related to autophagy by inhibiting the expression of Bcl-2 associated athanogene 3 (BAG3) in cisplatin-resistant ovarian epithelial cancer SKOV3 cells." (PMID 33117715, 2020). "Similarly, in thyroid carcinomas, leukemia, and ovarian cancer cells, BAG3 downregulation makes cells more susceptible to apoptosis-inducing therapy." (PMID 40507324, 2025). "Serum levels of BAG3 were significantly elevated in patients with liver, pancreatic, and ovarian cancers versus healthy controls." (PMID 41367874, 2025). "The limited sample sizes for each tumor type, especially for ovarian carcinoma, where the statistical power was low, restrict the strength of our conclusions regarding serum BAG3 levels." (PMID 41367874, 2025). "While our current study did not explicitly investigate the influence of metabolic changes on BAG3 secretion, the established reliance of ovarian cancer on oxidative metabolism suggests a potential metabolic link that warrants further exploration." (PMID 41367874, 2025). "Some previous studies have shown that in some human malignancies, such as thyroid cancer, cervical cancer, ovarian cancer, BAG3 is abnormally expressed, and it can modulate the progression of the disease." (PMID 36228497, 2022). "Another study showed that BAG3 silencing promotes the sensitivity of ovarian cancer cells to cisplatin." (PMID 30081850, 2018). "Importantly, elevated serum levels of BAG3 were detected in patients with liver, pancreatic, and ovarian carcinomas compared to healthy controls, substantiating BAG3’s potential as a circulating biomarker reflective of tumor burden." (PMID 41367874, 2025). "Studies have indicated that the expression levels of BAG3 in ovarian cancer tissues may influence the proliferation and apoptosis of cancer cells." (PMID 39596594, 2024). "The CX3CR1_macro subpopulation may play a role in promoting tumor progression in ovarian cancer with high expression of BAG3, IL1B, and VEGFA." (PMID 35935940, 2022). "For example, BAG3 can upregulate MCL1 by downregulating miR-29b, thereby inducing chemotherapy resistance to paclitaxel in ovarian cancer." (PMID 36262872, 2022). "Of note, down-regulation of BAG3 blocked CDDP−induced autophagy, thereby increasing CDDP sensitivity in ovarian cancer cells." (PMID 34746018, 2021). "Notably, ovarian carcinoma cells, particularly the chemoresistant line (PEA-2), display a distinct pattern of BAG3 secretion compared to other cancers." (PMID 41367874, 2025). "Notably, it has also been reported that BAG3 positively regulates the expression level of MCL-1 through the down-regulation of miR-29b and that the combined expression of BAG3 and MCL-1 confers resistance to chemotherapy-induced apoptosis in ovarian cancers." (PMID 30273361, 2018).
thyroid cancer (13 papers, 2014 to 2024). "Another protein known to modulate autophagy and apoptosis in thyroid cancer is Bcl2-associated athanogene 3 (BAG3)." (PMID 35846375, 2022). "For example, phosphorylation of BAG3 at Ser178 promoted, while non‐phosphorylatable BAG3 mutant decreased migration and invasion of thyroid cancer cells." (PMID 31657880, 2020). "Further, as shown in thyroid cancer cells harboring BRAFV600E mutation, the binding of the co-chaperone BAG3 to BRAF protected it from degradation by inhibiting HSP70-mediated delivery to the proteasome." (PMID 31841566, 2019). "Recently, it was demonstrated that BAG3 knockdown induces Epithelial Mesenchymal Transition (EMT) in thyroid cancer cells increasing their metastatic potential." (PMID 25149536, 2014). "We previously reported that BAG3 protein is specifically expressed in thyroid carcinomas and not in normal thyroid tissue and that its down-modulation results in enhancing apoptosis and decreasing cell survival in human thyroid carcinoma cells." (PMID 29487711, 2018). "BAG3 was initially identified as an anti-apoptotic protein and negative regulator of EMT expressed in multiple thyroid cancer cell lines." (PMID 35846375, 2022). "Moreover, it could be shown that BAG3 can be phosphorylated at serine 187 by the protein kinase C delta (PKCδ); this modified form of BAG3 then triggers the epithelial-mesenchymal transition and invasiveness of thyroid cancer cells." (PMID 28680391, 2017). "Furthermore, BAG3 is able to modulate BRAFV600E levels and activity in thyroid carcinomas." (PMID 29113311, 2017).
colorectal cancer (12 papers, 2014 to 2024). A primary or metastatic malignant neoplasm that affects the colon or rectum. "High expression of BAG3 was shown to be associated with the induction of cell proliferation, migration, and invasion in colorectal cancer, but with the suppression of apoptosis process in MCF7 cells." (PMID 33773557, 2021). "Using immunohistochemistry, this study found that BAG3 was markedly upregulated in colorectal cancer tissues and that BAG3 levels were significantly associated with tumor size and gender." (PMID 30081850, 2018). "Bcl-2-associated athanogene 3 (BAG3) is related with tumor cell proliferation, migration, invasion and chemoresistance in colorectal cancer." (PMID 35443865, 2022). "This is in contrast to an already published study that showed that Ctd in fact reduces the expression of BAG3 in human colorectal carcinoma cells." (PMID 35834635, 2022). "Despite previous reports on BAG3 expression in tumors, few studies have examined BAG3’s role in colorectal cancer." (PMID 30081850, 2018). "BAG3 overexpression in colorectal cancer can promote tumor proliferation, migration and invasion, while BAG3 knockout can inhibit these processes." (PMID 30081850, 2018). "The analysis demonstrated that the BAG3 protein was predominantly localized in the cytoplasm of the colorectal cancer cells." (PMID 30081850, 2018). "We examined the relationship between BAG3 protein expression and clinicopathological features in 90 patients with colorectal cancer." (PMID 30081850, 2018). "This study investigated the expression of BAG3 protein in colorectal cancer tissue specimens (n = 90) and matched adjacent normal colorectal tissues using immunohistochemical analysis." (PMID 30081850, 2018). "Taken together, these results indicate that BAG3 can promote colorectal cancer cell invasion and migration in vitro." (PMID 30081850, 2018). "BAG3 has been reported to sustain proliferation, migration and invasion in diverse cancer subtypes including colorectal cancer ovarian and hepatocellular cancer subtypes." (PMID 29644001, 2018). "The association between BAG3 expression and chemoresistance has not yet been examined in colorectal cancer." (PMID 30081850, 2018). "So BAG3 may be considered as a potential therapeutic target for anti-tumor therapy in colorectal cancer." (PMID 30081850, 2018). "Therefore, we conclude that BAG3 may be used as a potential biomarker or therapeutic target for colorectal cancer." (PMID 30081850, 2018). "For example, it was uncovered that the apoptosis-inducing potential of miR-217-5p can induced apoptosis via blocking multiple target genes PRKCI, BAG3, ITGAV and MAPK1 in colorectal cancer cells." (PMID 36352482, 2022). "We established in vitro models of BAG3 overexpression and knockout in HCT-116 cell line to further clarify the role of BAG3 in colorectal cancer tumorigenesis." (PMID 30081850, 2018). "MiR-217-5p could induce apoptosis in colorectal cancer cells by regulating multiple target genes, including PRKCI, BAG3, ITGAV, and MAPK1 in the ERK-MAPK signaling pathway." (PMID 35737029, 2022). "Similarly, AURKA, BAG3, NUBP1, and ANLN are all found to be dysregulated in colorectal cancer and involved in cancer progression and invasion." (PMID 34790220, 2021). "This study systematically examined the effects of BAG3 protein overexpression and knockout in human colon cancer HCT-116 cells for the first time and provided evidence of BAG3 as a potential therapeutic target against colorectal cancer." (PMID 30081850, 2018). "This study demonstrates that the expression of BAG3 in colorectal cancer tissue is higher than in non-tumor tissue in the same patient." (PMID 30081850, 2018). "We first examined BAG3 protein expression in clinical samples (tumor and matched adjacent non-tumor tissues) from colorectal cancer patients using immunohistochemistry." (PMID 30081850, 2018).
colorectal cancer (continued). "BAG3 protein expression was significantly higher in colorectal cancer tissues than in matched adjacent non-tumor tissues, which indicated that BAG3 protein may participate in CRC tumorigenesis and progression." (PMID 30081850, 2018).
glioma (12 papers, 2015 to 2025). A benign or malignant brain and spinal cord tumor that arises from glial cells (astrocytes, oligodendrocytes, ependymal cells). "Furthermore, loss of BAG3 profoundly reduced in vivo tumor growth in an orthotopic mouse glioma model." (PMID 32121220, 2020). "To further validate the correlation between BAG3 and immune infiltration in gliomas, we analyzed single-cell sequencing datasets of the KIRC from the TISCH database." (PMID 38297320, 2024). "Previous work by our research group has also shown that overexpression of BAG3 contributes to apoptosis resistance in GBM cells and that depletion of BAG3 in an orthotopic mouse glioma model leads to reduced tumor growth in vivo." (PMID 38655699, 2024). "BH3-only proteins down-regulate BAG3 levels and promote apoptosis of primary glioma cells." (PMID 29898735, 2018). "To date, the increasing literature has reported that BAG3 overexpression in glioma cells results in the stimulation of autophagy, whereas in osteosarcoma and melanoma cells, it promotes cell survival by sustaining the activation of NF-κB and preventing IKKγ degradation." (PMID 28144784, 2017). "We then investigated key autophagosomal (LC3B, p62, BAG3, Beclin1) and lysosomal (CTSB, LAMP2) molecules in 350 gliomas using immunohistochemistry, immunofluorescence, immunoblotting and qPCR." (PMID 26956048, 2016). "On the other hand, the use of inhibitors of the HSF-1/HSP90/BAG3 pathway increases the antineoplastic effect of AT101, reactivating caspase-dependent apoptosis in the U252 and U343 glioma cell lines through a downregulation of Bcl-2 and Mcl-1 and an increase of Bax and mitochondrial dysfunction." (PMID 30486451, 2018). "For BAG3, a non-canonical inducer of autophagy, even higher expression levels were found in normal appearing glioma-adjacent tissues and lowest grade pilocytic astrocytomas, WHO grade I." (PMID 26956048, 2016). "In the same study, silencing of Bag3 increased the response to ABT263 in different cancer cell lines not including gliomas." (PMID 26008975, 2015). "Furthermore, the non-canonical ALP stimulator BAG3 was mainly restricted to areas showing reactive gliosis in both normal appearing brain tissue as well as glioma tissues." (PMID 26956048, 2016).